RNU1-138P (RNA, U1 small nuclear 138, pseudogene)
Gene: Small nuclear RNA gene on chromosome 4 (113,420,323 to 113,420,486, forward strand). Ensembl gene ENSG00000206820.
Homologues: Orthologues: chimpanzee U1 (98% identical), macaque U1 (92% identical). Paralogues in human: RNU1-1 (90% identical), RNU1-2 (90% identical), RNU1-27P (90% identical), RNU1-28P (90% identical), RNU1-3 (90% identical), RNU1-4 (90% identical), RNVU1-18 (90% identical), RNVU1-29 (90% identical), U1 (90% identical), RNU1-89P (90% identical), RNVU1-28 (90% identical), RNVU1-7 (90% identical), and 134 more.